AHR (aryl hydrocarbon receptor)
Diseases named in the same sentence as AHR in open-access papers (continued):
Sharing a sentence is not in itself a finding about the gene and the disease.
psoriasis (continued). "Moreover, increased CYP1A1 activity in Th17 cells could potentially contribute to skin inflammation in patients with psoriasis by limiting the activation of AHR signaling in KCs." (PMID 33385398, 2021). "Therefore, the AHR pathway is an attractive target for the control of inflammatory skin disease, and topical application of tapinarof, a naturally derived AHR ligand, has shown promising efficacy in phase II clinical trials for psoriasis and atopic dermatitis." (PMID 33385398, 2021). "Moreover, AhR activity seems to be crucial modulator of the severity of psoriasis." (PMID 33499346, 2021). "Thus, AhR and autophagy appeared to be critical factors in psoriasis-related skin inflammation." (PMID 32235789, 2020). "Thus, AhR appears to play a critical role in modulating the severity of psoriasis." (PMID 24909886, 2014). "Similarly, AHR activation in keratinocytes restores the skin barrier by upregulating epidermal differentiation genes (loricrin and involucrin) and inhibits oxidative stress via Nrf2 signaling, thereby alleviating skin disorders like psoriasis and atopic dermatitis." (PMID 41513604, 2026). "The AHR is modulated by the novel drug, tapinarof, which was recently approved by the FDA in the topical treatment for psoriasis." (PMID 39519223, 2024). "Given the critical roles of both AHR and NF-κB signaling pathways in psoriasis, our study demonstrated that IDG acts as a ligand for AHR, activates the AHR signaling pathway, and inhibits the NF-κB signaling pathway." (PMID 39465158, 2024). "Tapinarof, a drug categorized as a therapeutic AHR-modulating agent (TAMA), has been developed as a topical treatment for both AD and psoriasis." (PMID 37834081, 2023). "This process of murine TRM formation seems to be dependent on the transcription factor aryl hydrocarbon receptor (AhR), which is also highly expressed on human skin and gastrointestinal TRM, and is a target for the topical treatment of psoriasis." (PMID 37144705, 2023). "A search in the PubMed database (up until June 2022) for articles with the specific keywords: “psoriasis,” “tapinarof,” “GSK2894512,” “aryl hydrocarbon receptor,” and “topical treatment” were carried out." (PMID 36226669, 2022). "Since AhR and ARNT are abundantly expressed in the skin, this complex has been targeted in the treatment of skin diseases such as atopic dermatitis (AD) and psoriasis." (PMID 35008717, 2021). "In both human psoriasis samples and an IMQ-induced model of skin inflammation, FICZ-induced AhR activation ameliorates inflammatory response." (PMID 33499346, 2021). "In human psoriasis lesion skin, the expression level of CYP1A1 and AhR was increased and LC3 was decreased compared to controls." (PMID 32235789, 2020). "AhR and CYP1A1 expression was significantly higher in TCDD-treated-psoriasis lesion skin tissues compared to TCDD-treated controls." (PMID 32235789, 2020). "The level of CYP1A1, AhR, and LC3 expression was determined by immunohistochemistry, and qPCR in human healthy skin (control) and human psoriasis lesion skin." (PMID 32235789, 2020). "To this end, we evaluated whether AhR activation regulated autophagy, or vice versa, in human keratinocytes under inflammatory conditions, as well as in skin biopsies from psoriasis patients, and explored the influence of AhR and autophagy on inflammation in skin biopsies from psoriasis patients." (PMID 32235789, 2020). "In this review, we summarized new insights regarding the pathogenesis of psoriasis, as it relates to AMPs, DCs, the IL23/IL17 axis, and AhR." (PMID 33050592, 2020). "In recent years, a growing number of studies have focused on the development of new drugs for psoriasis, including JAK inhibitors, Stat3 inhibitors, PDE4 inhibitors, TRK inhibitors, and AhR agonists." (PMID 33834028, 2020). "In contrast, serum levels of both AHR and CYP1A1 are elevated in patients with psoriasis compared to normal controls." (PMID 31683543, 2019).
psoriasis (continued). "Medicinal coal tar and soybean tar Glyteer activate both AHR and NRF2 and have been used to treat inflammatory skin diseases, such as atopic dermatitis (AD) and psoriasis." (PMID 31683543, 2019). "Immunohistological and real time PCR studies have demonstrated that the expression of AHR and ARNT is upregulated in the lesional skin of psoriasis, whereas CYP1A1 expression was significantly decreased compared to normal controls." (PMID 31683543, 2019). "Therefore, AHR may be a regulator of psoriasis and other chronic inflammatory skin diseases." (PMID 30513921, 2018). "Ingenuity pathway analysis showed that 26 out of 41 psoriasis-relevant genes modulated by AhR belong to the type I and II IFN pathway, which is known to be upregulated in psoriasis." (PMID 24909886, 2014). "Tapinarof, a first-in-class, nonsteroidal, topical aryl hydrocarbon receptor (AhR) agonist, represents a breakthrough in topical psoriasis management." (PMID 40948748, 2025). "Conversely, AHR ligation by FICZ ameliorated the transcriptional profile of ex vivo skin biopsies from psoriasis patients and reduced the severity of psoriasiform inflammation in mice, further supporting a beneficial role of AHR in psoriasis." (PMID 40004095, 2025). "Tapinarof, an AhR agonist, is FDA-approved for the topical treatment of psoriasis." (PMID 40162433, 2025). "In recent years, the role of AhR in the pathogenesis of various skin diseases such as non-melanoma skin cancer, melanoma, psoriasis, atopic dermatitis, acne, and hidradenitis suppurativa has been reported." (PMID 38361944, 2024). "Its value as a topical treatment in inhibiting scarring has, however, been demonstrated, and Aryl hydrocarbon receptor agonists (of which KYNA is one, and including the FDA-approved tapinarof) have been shown to have benefits in both psoriasis and atopic dermatitis." (PMID 39201768, 2024). "Tapinarof, a topical AHR agonist, has been approved by the FDA for psoriasis." (PMID 37511138, 2023). "Therefore, the strategy to control IL-37 expression using AHR modulators such as tapinarof and GFF should be beneficial for the treatment of aging as well as inflammatory skin diseases including AD and psoriasis." (PMID 35663970, 2022). "Conversely, in chronically inflamed skin disease, such as atopic dermatitis (AD) and psoriasis, high levels of non-canonical AhR-partner molecules are expressed." (PMID 34944067, 2021). "In this study, we identified hypomethylation and overexpression of AhRR in the lesional epidermal skin of patients with psoriasis, and TCDD reacted with AhRR, AhR repressor, to confirm the effect of increasing pro-inflammatory cytokines in psoriasis skin tissues along with HaCaT cells." (PMID 34884515, 2021). "Conversely, AHR ligation by the tryptophan-derived ligand 6-formylindolo[3,2-b]carbazole (FICZ) ameliorated the transcriptional profile of ex vivo skin biopsies from patients with psoriasis and reduced the severity of psoriasiform inflammation in mice." (PMID 33385398, 2021). "This is a possible scenario, as there is evidence that AhR expression in non-hematopoietic cells prevents neutrophilia in psoriasis and during influenza virus infection." (PMID 33659010, 2021). "Nevertheless, because we are not dissecting the pathogenic role of Th17 cells in psoriasis but rather using them as a robust model system to measure CYP1A1 enzymatic activity, their usage is not in contrast with the beneficial role of the AHR pathway." (PMID 33385398, 2021). "To verify whether AhR or autophagy had a role in psoriasis pathology, we investigated the effects of TCDD-induced AhR activation, autophagy stimulation by rapamycin, or autophagy inhibition by chloroquine on the production of proinflammatory cytokines." (PMID 32235789, 2020). "Although imiquimod-induced skin inflammation is popular as a psoriasis model, attention should be paid because imiquimod is degraded by CYP1A1 so the efficacy of AHR agonists may partly rely on this effect in the imiquimod model." (PMID 31683543, 2019).
psoriasis (continued). "Combining the analysis of psoriasis patient skin biopsies with that of a mouse model of psoriasiform inflammation, we showed that AhR signaling in nonhematopoietic cells plays a central role in preventing excessive skin inflammation." (PMID 24909886, 2014). "Indeed, data about AHR expression and activation in psoriasis compared to non-lesional or healthy skin are sometimes conflicting." (PMID 40004095, 2025). "Similarly, AhR agonists demonstrated favorable therapeutic effects in an imiquimod (IMQ)-induced mouse model, while the AhR antagonist CH-223191 exacerbates psoriasis-related gene expression in patient biopsies by blocking the AhR pathway." (PMID 41425939, 2025). "A critical role for AHR in psoriasis was uncovered in 2014, when we reported that a lack of AHR signalling exacerbates the severity of psoriasiform inflammation in mice, by unleashing excessive production of chemokines and cytokines by keratinocytes in response to proinflammatory stimuli." (PMID 40004095, 2025). "For example, the activation of AhR in CD4+ T cells can drive differentiation toward the Th17 and Th22 subtypes, which may inadvertently trigger skin inflammation in patients suffering from AD or psoriasis." (PMID 39939818, 2025). "AhR expression and signaling are altered in many inflammatory skin disorders such as AD and psoriasis, and clinical trials with tapinarof (first-in-class, non-steroidal, topical AhR agonist) have validated AhR as a therapeutic target capable of delivering significant efficacy." (PMID 39722037, 2024). "Interestingly, in agreement with our data in mice, patients with psoriasis displayed increased CYP1A1 enzymatic activity compared with healthy donors, suggesting that dysregulation of the AHR/CYP1A1 axis may play a role in inflammatory skin disease." (PMID 33385398, 2021). "Given the key role of the TNF-α/IL-23/IL-17A axis in the pathogenesis of psoriasis, it could be hypothesized that polycyclic aromatic hydrocarbons (PAHs), such as TCDD, via AHR activation have a potential impact on the development or aggravation of the disease." (PMID 33921372, 2021). "Third, we could not evaluate the mechanisms by which AhR and autophagy regulate the adaptive immune system, for instance, by modulating the levels of cytokines critical in psoriasis pathogenesis, such as IL-17, IL-22, and IL-23 in the skin." (PMID 32235789, 2020). "Further, treatment of an imiquimod-induced psoriasis murine model with the AHR agonist FICZ decreased psoriasis and decreased the expression of psoriasis-related genes, effects which were dependent on the stromal expression of AHR and interaction with the adaptive immune system." (PMID 30513921, 2018). "Additionally, the article shows the cornerstones in the management of psoriasis along with the various upcoming therapies in the pipeline and those under therapeutic trials enumerating a few such as ROCK inhibitors, JAK inhibitors, AhR agonists, and S1P agonists." (PMID 37228538, 2023). "Importantly, patients with psoriasis displayed reduced activation of the AHR pathway and increased CYP1A1 enzymatic activity compared with healthy donors, suggesting that dysregulation of the AHR/CYP1A1 axis may play a role in inflammatory skin disease." (PMID 33385398, 2021). "Thus, we suggested that AhR activation by environmental pollutants such as dioxin (TCDD) could affect the autophagic process, and might contribute to the pathogenesis of chronic inflammatory skin disorder, including psoriasis." (PMID 32235789, 2020). "However, both murine and human keratinocytes lacking AhR were overreactive to proinflammatory stimuli, suggesting shared aspects of pathology, which may diverge later on in the chronic phase of human psoriasis." (PMID 24909886, 2014).
psoriasis (continued). "In contrast, the lack of effect of AhR-mediated activation on other relevant psoriasis gene signatures in human samples, such as the antimicrobial response and tissue remodeling, which are affected in the mouse model, could be the result of the short-term culture of the skin biopsies." (PMID 24909886, 2014).
autoimmune disease (96 papers, 2010 to 2026). A disorder resulting from loss of function or tissue destruction of an organ or multiple organs, arising from humoral or cellular immune responses of the individual to their own tissue constituents. "Increased AhR activity is associated with autoimmune disease pathology and preclinical disease models, with AhR agonists suppressing inflammation in models of inflammatory bowel disease, SLE, and rheumatoid arthritis." (PMID 39880074, 2025). "A growing number of studies have shown multiple associations of gut microbiota with AhR and autoimmune diseases." (PMID 36110860, 2022). "Previous studies have shown that AhR is associated with many autoimmune diseases, including multiple sclerosis, rheumatoid arthritis, inflammatory bowel disease, SLE, and so on." (PMID 36110860, 2022). "Deregulation of the AhR pathway is implicated in several diseases, including autoimmune diseases and cancer, rendering AhR a promising target for drug development and host-directed therapy." (PMID 33668313, 2021). "Our findings suggest that the immunosuppressive activity of gold compounds can be improved by introducing planar NHC ligands to activate the AHR-associated immunosuppressive pathway, thus expanding their potential clinical application for autoimmune diseases." (PMID 31909202, 2020). "The activation of aryl hydrocarbon receptor (AhR) has been shown to reduce immune responses, leading to suppression of autoimmune diseases, and possibly reduce inflammation associated with Crohn’s disease as well." (PMID 28549934, 2017). "The aryl hydrocarbon receptor (AhR) is extensively expressed in immune cells, crucial for immune responses and its abnormal signaling may be linked to autoimmune diseases." (PMID 38236441, 2024). "The activation of the AhR pathway in the intestine by dietary or microbiome metabolites triggers immunoregulatory effects that have been recognized to be implicated in the pathogenesis of autoimmune disorders." (PMID 35308285, 2022). "The incidence and prevalence of autoimmune diseases continue to increase and current studies have shown that genetic susceptibility accounts for approximately 30% of all autoimmune diseases, the remaining 70% is due to environmental factors, which are closely related to AhR." (PMID 36110860, 2022). "Rheumatoid arthritis (RA) is an autoimmune disease that may be associated with gut microbiota via the aryl hydrocarbon receptor (AhR)." (PMID 32232043, 2020). "Both PM and the AHR have strong associations with autoreactive T cells and autoimmune disease." (PMID 30574142, 2018). "The aryl hydrocarbon receptor (AhR) is a widely studied ligand-activated cytosolic transcriptional factor that has been associated with the initiation and progression of various diseases, including autoimmune diseases, cancers, metabolic syndromes, and allergies." (PMID 36601108, 2022). "Considering the immunosuppressive effects of AhR ligands on autoimmune disease, it is rational to propose that AhR activation in the tumor microenvironment is associated with an increased proportion of Treg cells and may explain (at least in part) the tumor-promoting properties of TCDD." (PMID 29487603, 2018). "Targeting this axis, for instance through combined HIF-1α inhibitors and IDO1/AhR pathway agonists, holds promise as a novel metabolic intervention strategy for autoimmune diseases." (PMID 41869303, 2026). "Several ongoing clinical trials are evaluating AhR agonists for the treatment of other inflammatory and autoimmune diseases, including inflammatory bowel disease." (PMID 41321307, 2025). "This interaction with AhR suggests its potential use in therapeutic strategies for autoimmune diseases such as MS and rheumatoid arthritis." (PMID 39684480, 2024). "Other than autoimmune diseases, previous studies have demonstrated that AhR activation by KYNA, ITE, as well as TCDD remarkably decreased the frequency of Tfh cells in mice infected with the influenza virus." (PMID 37382269, 2023).